TMEM120A (transmembrane protein 120A)
Description:
Multifunctional protein involved in mechanosensation, and plays an essential role in lipid metabolism and adipocyte differentiation. May function as a potential ion channel involved in sensing mechanical stimuli. Mediates the mechanosensitivity of the PKD2-TMEM120A channel complex through direct physical interaction. TMEM120A seems to affect mechanosensation by inhibiting PIEZO2 channels, possibly by altering cellular lipid content (By similarity). TMEM120A is structurally similar to a lipid-modifying enzyme, ELOVL7, and contains a bound coenzyme A molecule, which suggests it might function as an enzyme in lipid metabolism. Additionally, implicated in innate immune response against Zika virus. Acts as a key activator of the antiviral signaling involving STING1.
Synonyms: TACAN; TMPIT; NET29
Tractability: Small molecule: a structure with a bound ligand is known. Antibody: UniProt places it where antibodies can reach, with high confidence; its Gene Ontology location is reachable by antibodies, with high confidence; UniProt predicts a signal peptide or a membrane-spanning region. PROTAC: ubiquitination databases record sites on it; its protein half-life has been measured.
Gene: Protein-coding gene on chromosome 7 (75,986,831 to 75,994,656, reverse strand). Ensembl gene ENSG00000189077.
Subcellular location: Cell membrane; Nucleus inner membrane; Endoplasmic reticulum
Gene Ontology:
Molecular function: coenzyme A binding; monoatomic ion channel activity; protein binding
Biological process: antiviral innate immune response; fat cell differentiation; protein heterooligomerization; protein homooligomerization; detection of mechanical stimulus involved in sensory perception of pain; monoatomic ion transmembrane transport
Cellular component: endoplasmic reticulum; plasma membrane; membrane; nuclear inner membrane
Genetic constraint (gnomAD): Loss-of-function variants: 45 observed, 46.13 expected, observed/expected ratio (o/e) 0.98, 90% interval 0.77 to 1.25. The synonymous counts are far from expectation, so gnomAD's model fits this gene poorly and the ratio says little. Missense variants: 424 observed, 405.11 expected, observed/expected ratio (o/e) 1.05, 90% interval 0.97 to 1.13. Synonymous variants: 204 observed, 159.93 expected, observed/expected ratio (o/e) 1.28, 90% interval 1.14 to 1.43.
Homologues: Orthologues: chimpanzee TMEM120A (97% identical), mouse Tmem120a (95% identical), guinea pig TMEM120A (94% identical), rat Tmem120a (94% identical), dog TMEM120A (91% identical), pig TMEM120A (85% identical), tropical clawed frog tmem120a (75% identical), zebrafish tmem120aa (69% identical), zebrafish tmem120ab (62% identical), Drosophila melanogaster CG32795 (47% identical), Caenorhabditis elegans tmem-120 (42% identical). Paralogues in human: TMEM120B (69% identical).
Diseases named in the same sentence as TMEM120A in open-access papers:
TMEM120A is named in the same sentence as 13 diseases in open-access papers, as found by Europe PMC text mining. Sharing a sentence is not in itself a finding about the gene and the disease. The quoted sentences say what the papers report.
channelopathy (2 papers, 2024 to 2025). Channelopathies are a group of diseases caused by the dysfunction of ion channel subunits or their interacting proteins. "It is noteworthy that a functionally analogous autonomously acquired PIEZO2 channelopathy is proposed in DOMS and amyotrophic lateral sclerosis as well due to the dissociation of the auxiliary connection of the inhibitor protein ligands of PIEZO2, like MyoD or TMEM120A." (PMID 39682086, 2024).
lipodystrophy (2 papers, 2022 to 2023). A congenital or acquired disorder characterized by abnormal loss or redistribution of the adipose tissue in the body. "TMEM120A deficiency is reported to broadly impact lipid metabolism and causes lipodystrophy by altering genome topology." (PMID 37754271, 2023). "A subset of these were under Tmem120A positional regulation (highlighted in yellow), but they tended to be relevant to fat metabolism and lipodystrophy associated comorbidities." (PMID 35027552, 2022). "Our data indicate TMEM120A genome organisation functions affect many adipose functions and its loss may yield adiposity spectrum disorders, including a miRNA-based mechanism that could explain muscle hypertrophy in human lipodystrophy." (PMID 35027552, 2022).
Obesity (2 papers, 2015 to 2022). Accumulation of substantial excess body fat. "In humans, the mRNA level of TMEM120A was ~25% lower in adipose tissue of obese Arizona Pima Native Americans22 and 40% lower in obesity with diabetes in Asian Indians (data obtained from GEO dataset, GDS3665)." (PMID 35027552, 2022). "Further work dissecting out TMEM120A critical miRNA targets could potentially enable miRNA therapies targeting separately its muscle mass function for muscle disorders and its fat metabolic functions for obesity." (PMID 35027552, 2022). "Thus it is possible that the TMEM120A and B fat-specific nuclear envelope transmembrane proteins may play a contributory role in the tissue-specific pathology of this disorder or in the wider problem of obesity." (PMID 26024229, 2015).
hyperlipidemia (1 paper, 2022). "In contrast, Ad-Tmem120a−/− mice had no hyperlipidemia, no increase in hepatic lipid droplet size, and no significant increase in liver mass." (PMID 35027552, 2022).
virus infection (1 paper, 2022). "In summary, we demonstrate the utility of ORF-based gain-of-function screening in uncovering host factors for virus infection and establish TMEM120A as a new antiviral restriction factor and an activator of STING signaling." (PMID 35013224, 2022).
Zika virus infection (1 paper, 2022). "TMEM120A overexpression significantly inhibits ZIKV replication, while TMEM120A knockdown increases ZIKV infection in cell lines." (PMID 35013224, 2022). "Here the authors perform a gain-of-function screen to identify factors involved during Zika virus infection and identify TMEM120A as a key factor in the STING mediated immune responses." (PMID 35013224, 2022). "Here we report a human genome-wide overexpression screen to identify host factors that regulate ZIKV infection and find TMEM120A as a ZIKV restriction factor." (PMID 35013224, 2022). "TMEM120A knockdown indeed increased ZIKV infection in both Huh7 and U87MG cells showing that it is rate-limiting for viral function, much like a previous factor we discovered, IFITM327." (PMID 35013224, 2022). "We found that CTD inhibited ZIKV infection to a similar level as the full-length TMEM120A, indicating the importance of CTD for the antiviral effect." (PMID 35013224, 2022). "We found that ectopic expression of TMEM120A significantly suppressed ZIKV infection in both Huh7 and U87MG cells." (PMID 35013224, 2022). "Collectively, these data demonstrate that Tmem120a deletion increases ZIKV infection through attenuating innate immune responses in MEFs." (PMID 35013224, 2022). "In addition, the mRNA levels of Ifnb and a number of Isgs were also decreased in Tmem120a−/− MEFs with 2′, 3′-cGAMP stimulation or ZIKV infection." (PMID 35013224, 2022). "Moreover, Tmem120a knockout in mice facilitates ZIKV infection in primary mouse embryonic fibroblasts (MEF) cells." (PMID 35013224, 2022). "Given the strong antiviral activity of TMEM120A in vitro, we further tested whether TMEM120A inhibits ZIKV infection in vivo." (PMID 35013224, 2022). "In U87MG cells, TMEM120A overexpression increased the transcription of IL6, IL8, and IFIT2 to a similar level as STING overexpression induced after ZIKV infection." (PMID 35013224, 2022). "And ZIKV infection reduced the protein level of STING in luciferase but not TMEM120A overexpressing U87MG cells in our study." (PMID 35013224, 2022). "We found that STING knockdown increased ZIKV infection to the same level in both luciferase and TMEM120A groups, indicating STING knockdown is epistatic to the antiviral phenotype of TMEM120A overproduction without affecting TMEM120A mRNA levels." (PMID 35013224, 2022).
infection (1 paper, 2022). The state of being infected such as from the introduction of a foreign agent such as serum, vaccine, antigenic substance or organism. "Besides ZIKV, TMEM120A also inhibited infection by dengue virus (DENV), yellow fever virus (YFV), two members of the Flavivirus genus, and herpes simplex virus type 1 (HSV-1), a double-stranded DNA virus in U87MG cells." (PMID 35013224, 2022). "As expected, Tmem120a deletion remarkably increased ZIKV or HSV-1 infection in Tmem120a−/− MEFs." (PMID 35013224, 2022).
TMEM120A also shares sentences with these, for which no sentence is quoted: amyotrophic lateral sclerosis (1 paper); cancer (1); Hepatic steatosis (1); injury (1); muscle disorders (1); partial lipodystrophy (1).